RAC1 (Rac family small GTPase 1)
Diseases named in the same sentence as RAC1 in open-access papers (continued):
Sharing a sentence is not in itself a finding about the gene and the disease.
tumor (continued). "Then, we picked out 8 HAIRGs (VEGFA, CTNNB1, PPARG, HSP90AA1, HMOX1, LGALS3, SPP1, and RAC1) from the 17 HAIRG model through the LASSO Cox regression, upregulated genes accounted for 7/8 in tumor tissue, which was shown by a heat map." (PMID 35069936, 2022). "AZA1 can effectively inhibit the activation of Cdc42 and Rac1, reduce the signal transduction of the PAK pathway, and inhibit tumor growth." (PMID 35154449, 2022). "As known, the endothelial migration is essential for tumor cell invasion, where RAC1–NADPH oxidase complex induce expression of matrix metalloproteinases (MMPs) after growth factor and tumor promoter stimulation." (PMID 36452505, 2022). "Even so, other therapeutical strategies have been used to treat tumours bearing this signature, such as: preventing RAC1 localization at the plasma membrane, hampering GTP binding, blocking GEF/RAC1 interaction or targeting its effector molecules." (PMID 34827551, 2021). "Immune infiltration analysis showed that the expressions levels of COL3A1, RAC1, FN1, and SDC2 in CD4+T cells were significantly higher than those in tumor cells, especially regulatory T cell infiltration was significantly increased in BM tumors." (PMID 34229299, 2021). "In the context of chronic lymphocytic leukemia, CDC42 upregulation, together with downregulation of RAC1 and RHOA, upon direct contact with tumor cells, impairs migration of T cells and therefore immunosurveillance." (PMID 33406731, 2021). "In this study, Rac1, RhoA and CDC42 were all required for tumour cell adhesion to the EC, but only CDC42 was required for the intercalation of tumour cells into the EC." (PMID 34374417, 2021). "Many studies indicated that the expression of these proteins, including RHOA, RHOC, RAC1, RAC2 and CDC42 are upregulated and/or their activities are dysregulated through GEFs, GAPs or GDIs in tumor tissue." (PMID 33406731, 2021). "Co-targeting BRD4 and RAC1 precipitated very significant anti-growth effects in BRCA cells in vitro and inhibited tumor growth in vivo." (PMID 34803511, 2021). "Intriguingly, RAC1 is enclosed into these exosomes and participates in Integrin, EGFR, CCKR, and FGF signaling pathways in the tumor microenvironment." (PMID 34326687, 2021). "The present study found that Rac1/Cdc42 was highly expressed in RMS, and the IHC results showed that the protein expression was homogeneous in all tumor regions." (PMID 34221974, 2021). "Because our patient tumor sample at progression and the PDX.008.CL cells showed also an increase in RAC1 copy numbers, we chose to investigate the effects of RAC1 amplification in the present study." (PMID 34638434, 2021). "Given its crucial role in normal pancreatic endocrine development and tumor progression, both of which involve EMT, we analyzed here the role of the small GTPase RAC1." (PMID 34771704, 2021). "Recent studies have shown that extra centrosomes induce Ras-related C3 botulinum toxin substrate 1 (RAC1) activation by increasing microtubule nucleation and then promote tumour invasion through RAC1." (PMID 33663596, 2021). "In terms of proliferation, Rac1 has been reported to promote SC proliferation by suppressing NF2; however, this leads to tumor formation, which often results from an unsuccessful nerve regeneration." (PMID 34062912, 2021). "The small GTPase RAC1 and its guanine nucleotide exchange factor (GEF) TIAM1 promote cell survival, proliferation, migration, and invasion, processes required for tumor growth and metastasis." (PMID 34758330, 2021). "The absence of S1PR1 leads to Y1175 phosphorylation, a subsequent internalization of VEGFR2, ephemeral Rac1 activity, and strong ERK1 activity which results in ineffective tumor angiogenesis." (PMID 34690821, 2021). "The subsequent comparison between the adjacent tumor and normal tissue disclosed a correlation between RAS activation and active RAC1 levels." (PMID 34831012, 2021).
tumor (continued). "The most prominent of these routes, with remarkable significance for tumour growth and progression, is represented by Ras-GTP interacting with PI3K, which can then activate Rac1." (PMID 32456244, 2020). "HRAS, RAF, RAC1, and ERK1/2, as targets of tumor-targeting agents, are closely related to the prevention and treatment of tumors." (PMID 32419796, 2020). "Increasing studies showed that both the Rho family and MMP family, including Rac1/2/3, CDC42, RhoA, RhoC, MMP2, and MMP9, are highly expressed in a variety of tumor tissues and are directly correlated with tumor migration and invasion." (PMID 33377649, 2020). "The top 10 downregulated genes are involved in different signalling pathways, such as the CHN2 gene in the regulation of RAC1 activity, the FOS gene in EGFR signalling and ITGA7 in integrin pathways and Akt signalling and in tumour initiation and progression." (PMID 32613561, 2020). "Previous studies have shown that RhoA/Rac1 GTPase is an important link with Hippo, ERK, and PAK signaling pathways involved in tumor progression 27-34." (PMID 33042270, 2020). "RAC1, via PAK1, drives TGFβ1-induced prostate cancer cell EMT, as well as EMT and tumor growth in gastric cancer." (PMID 33266416, 2020). "In parallel, in accordance to previous reports that CD44 regulates Rho-family of GTPases to promote tumor progression, we show that SRGN promoted cytoskeleton reorganization via inducing Rac1 and CDC42 activation." (PMID 31898491, 2020). "PKCι-mediated Rac1 activation can stimulate MEK-ERK signaling in pancreatic cancer cell lines, leading to increased anchorage-independent growth in vitro and promoting tumor growth and metastasis in an orthotopic mouse model." (PMID 32309283, 2020). "In addition to the importance of the clarification of this pathway inhibition mechanism by TcdA in C. difficile infection, targeting Rac-1 with TcdA, which resulted in the Wnt/β-catenin pathway and cell proliferation inhibition, may be one strategy to control tumor growth." (PMID 32983019, 2020). "Our result showed that the knockdown Rac1 moderately decreased the growth of MCF-7DR tumors, while the doxorubicin treatment only slightly reduced the tumor growth of MCFDR." (PMID 32193458, 2020). "Strikingly,combination treatment of doxorubicin and Rac1 depletion, most significantly decreased the MCF7DR tumor growth." (PMID 32193458, 2020). "PREX1 activates insulin growth factor 1 receptor/insulin receptor signaling, as well as Rac1, phosphoinositide 3 kinase/protein kinase B, and mitogen-activated and extracellular-regulated kinase signaling, and PREX1 promotes cell and tumor viability." (PMID 32629428, 2020). "Rac1-GTP interacts with different downstream effector molecules, thus affecting tumor invasion and metastasis." (PMID 31338333, 2019). "Univariate analysis showed that TUFT1 expression was positively correlated with tumor size, histological grade, axillary lymph node metastasis, and Rab5-GTP and Rac1-GTP expression (p = 0.024, p = 0.009, p = 0.000, p = 0.000, and p = 0.029, respectively)." (PMID 31572059, 2019). "Conclusively, ANXA5 downregulation inhibited hepatocarcinoma cell induced primary tumor growth of mice via downregulating CRKI/II and RAC1." (PMID 29802377, 2018). "Our data suggest ITGA9, as a suppressor of HCC, prevents tumor cell migration and invasiveness through FAK/Src-Rac1/RhoA signaling." (PMID 29951557, 2018).
tumor (continued). "Additional studies based on different transgenic mouse models have confirmed that Rac1 is essential for dissemination and invasion of NPM-ALK+ tumor cells." (PMID 30558116, 2018). "On 21st d following tumor cell implantation, the decreases of CRKI/II and RAC1 expressions in primary tumors of Hca-P-ANXA5-shRNA1 group mice were of statistical significances." (PMID 29802377, 2018). "To investigate this in K14 HPV-8 and K14 HPV-8/Rac1-EKO mice, we carried out immunostainings for γH2AX on tumor samples." (PMID 27506937, 2016). "Icariin was also reported to significantly inhibit tumor cells migration and invasion of human gastric adenocarcinoma cell line BGC-823 via the down-regulation of Rac1 and VASP." (PMID 27649234, 2016). "The small Rho GTPases Rac1, RhoA and Cdc42, are key mediators in the Wnt/PCP pathway and important contributors to tumor migration and invasion." (PMID 26689985, 2016). "Activated Rac1 in turn triggers JAK-STAT pathway activation, resulting in rapid tumor growth and metastasis." (PMID 27588399, 2016). "Consist with the previous researches, our data demonstrated that inhibition of REPS2 would activate RalBP1/RAC1/CDC42, increase MMP2/9, thus promote tumor invasion and metastasis." (PMID 27120794, 2016). "Targeting Rac1 and subsequently inhibiting its activity make TIPE2 a potential therapeutic strategy to suppress the invasiveness of tumor cells." (PMID 27556698, 2016). "Recent studies have shown that miR-124 mitigates tumor cell migration by directly targeting ROCK and Rac-1, both of which are components of the RhoA-ROCK cascade that regulates actomyosin contractility." (PMID 25969668, 2015). "By repressing Pak1 expression, Rb could prevent the Rac1 hyperactivity that has been previously related to the disruption of adhesive structures in epithelial cells, a process that can exacerbate metastasis by promoting detachment of tumor cells from the primary site." (PMID 26555075, 2015). "While both GSDMB isoforms promote cell motility and invasion through activation of the Rho-GTPases Rac-1 and Cdc-42 in vitro, their analysis in xenograft mouse models showed that only GSDMB-2 increases tumor growth and metastasis." (PMID 24675552, 2014). "ERBB4 is overexpressed in ES cell lines derived from advanced tumours as well as in human metastatic ES lesions, and leads to activation of PI3K-Akt, focal adhesion kinase (FAK), and the Rac1 GTPase, a well-established mediator of cell migration and invasion." (PMID 23681745, 2013). "In tumours isolated from each of three separate mice, ERBB4 kd led to almost complete abrogation of Akt phosphorylation and significantly reduced Rac1 (p < 0.05), and FAK activation (p < 0.05)." (PMID 23681745, 2013). "Rac1 is Rho GTPase involved in VEGF signaling pathway, while endoglin is a TGF-β co-receptor and its expression is highly elevated in tumor blood vessels." (PMID 23593103, 2013). "Consistent with this, silence of Rac1 expression by specific siRNA abolished the inhibition effect of TIPE2 on migration and invasion of tumor cells." (PMID 24274578, 2013). "PI3K, which interacts directly with and is regulated by ERBB4, is required for Rac1 activation, and PI3K activation supports metastasis in many tumour types." (PMID 23681745, 2013). "Up-regulation of Rac1 activity by P-REX1 and Tiam1 GEFs has been described independently of tumour HER2 status, although the latter finding is disputed." (PMID 22689141, 2012). "HGF induction of Rac1 activation and MT1-MMP production implied that cell migration and proteolysis are two essential processes during tumor invasion and metastasis." (PMID 22242160, 2012). "Proteins that decrease Rac1 activity through hydrolysis of GTP, GTPase activating proteins (GAPs), act as tumor suppressors." (PMID 23300597, 2012).
tumor (continued). "Therefore we hypothesized that HGF induces Rac recruitment at ruffling sites, which may prolong the membrane expression of CXCR4/Rac-1, and reduce the CXCR4 endocytosis caused by chemoattractants and/or CXCR4 antibodies, thereby stimulating the chemotaxis and migration of tumor cells." (PMID 22242160, 2012). "Isolated side population (SP) cells representing putative CSCs from human NSCLA cells contained elevated levels of Rac1-GTP, enhanced in vitro migration, invasion, increased in vivo tumor initiating and lung colonizing activities in xenografted mice." (PMID 21347385, 2011). "Thus, p190B may facilitate tumor formation and progression by enhancing Rac1 activity." (PMID 20860838, 2010). "As our results suggest, Tiam1-mediated Rac1 activation may feed back to augment nuclear Wnt signalling, leading to sustained Tiam1/Rac1 signalling and as a consequence, the enhanced transcription of target genes that may be important for tumour initiation and/or progression." (PMID 18826597, 2008). "Genes of this pathway up-regulated in CC tumor cells were JUN, MYC, FZD2, RAC1, GSK3B and CTNNB1, and a few others." (PMID 17822553, 2007). "Our results demonstrate that lipid agonist-induced tumor cell invasion requires MT1-MMP, and its signaling occurs via LPA1, S1P1, Rac1, and Cdc42." (PMID 17156449, 2006). "In contrast, expression of Rac1 Cdc42, Rho-GDI and ERK2 in both grade I and grade III tumours was similar to that of MCF-7 cells." (PMID 12237774, 2002). "RAC1, a central component of the Rho family small GTPase signaling network, plays pivotal roles in cytoskeletal remodeling, migration, invasion, and EMT during tumor progression." (PMID 41328352, 2026). "In this respect, ATOX1 plays an important role in vascular remodeling by promoting copper- and RAS-related C3 botulinum toxin substrate 1 (RAC1)-dependent migration of vascular smooth muscle cells, macrophage infiltration and LOX activation, thereby contributing to tumor angiogenesis." (PMID 40721800, 2025). "This crosstalk between Wnt signaling, Rac1, and mTORC2 underscores the metabolic adaptability of cancer cells, where both canonical and non-canonical pathways converge to drive tumor survival." (PMID 40917745, 2025). "Previous research found that TIPE3 may promote tumor progression via increasing the expression of RAC1, while other TIPE family members also interact with RAC1 directly during tumor progression." (PMID 40904408, 2025). "Expression of TIPE3 and RAC1 in the blood samples of LUAD patients should also be explored, as blood samples could be easily accessed compared with tumor tissues." (PMID 40904408, 2025). "However, G-5555 partially re-sensitized Rac1-driven BRAFi-resistant tumor cells to BRAF inhibition, both for Vav1 over-expressing cells and for cells expressing the clinically relevant Rac1 P29S constitutively active mutant." (PMID 41109929, 2025). "This is achieved through the nuclear translocation of RAC1 and the subsequent transcriptional activation of the epigenetic modifier TET2 leading to increased levels of p21 and p27, which significantly influence tumour behaviour." (PMID 40715090, 2025). "Furthermore, the p110⍺ isoform of PI3K is known to regulate Rho and Rac1 GTPase activity in acinar cells, and inactivation of p110⍺ inhibits ADM and tumor formation in vivo." (PMID 40156071, 2025). "Importantly, blocking Rac1 activity by a specific inhibitor NSC23766 reverses the EMT program and attenuates CGN-mutant tumor growth." (PMID 38424547, 2024). "Rac1 and Cdc42 activate PAK2, facilitating cytoskeletal dynamics and tumor progression." (PMID 39769207, 2024). "Additionally, the Wiki pathway involving RAC1/PAK1's implication in cell proliferation, angiogenesis and tumour growth, and the Panther pathways for inflammation, oxidative stress and apoptosis signalling were also listed." (PMID 39281650, 2024).
tumor (continued). "While we were not able to measure RAC1 activity in tumours directly, it would be desirable to do this in the future, using such tools as a RAC1 FRET biosensor mouse model." (PMID 38712822, 2024). "Our findings indicate that inhibition of Rac1 activation by the compound 1A-116 reverses 5-FU resistance in CRC cells, decreases tumor growth, and prevents metastasis development, suggesting a therapeutic application of 1A-116 for the treatment of therapy-resistant CRC." (PMID 39513883, 2024). "In addition, p120 is essential for anchorage-independent growth of tumor cells via regulating ROCK pathway, ablation of p120 completely blocked Rac1– and Src–mediated anchorage-independent growth." (PMID 39498333, 2024). "Studies of RAC1 in orthotopic mouse models show that RAC1 accelerates tumorigenesis and progression, and the lack of RAC1 expression suppresses tumor formation." (PMID 39001533, 2024). "DIRAS1 is a well-known tumor suppressor and the ability of DIRAS1 to significantly diminish the prenylation of RAC1B, and to a lesser extent RAC1, provides a new mechanism through which DIRAS1 may inhibit oncogenic signaling by these small GTPases." (PMID 37059183, 2023). "Interestingly, in endometrial cancer cells both Rac1—an indicator of tumor cell migration and invasion, and MMP-2—an indicator of tumor metastasis and primary tumor growth—were downregulated by IL-37." (PMID 36769226, 2023). "Therefore, Rac1 activity enhanced by PA through the CD36-Src-Akt signaling pathway played the key role in mediating actin-remodeling and promoting tumor metastasis." (PMID 37612265, 2023). "Compared to blank group (no tumor burden) both the NC and RAC1-OE groups showed tumor burden in MRI results, and the primary focal tumor was significantly heavier in the RAC1-OE group than the NC group in weight (P < 0.001)." (PMID 37202394, 2023). "RAC1 inhibitors, such as the compound GYS32661 proved to be effective in tumor therapy." (PMID 36969076, 2023). "Pharmacodynamics study performed by estimating the transcript levels of Rac1, Cdc42, HIF-1α, β-catenin and DDX3 in the tumor tissue reveled a significant downregulation of these important metastasis markers in the combination group as compared to the drug alone group." (PMID 37024613, 2023). "RAC1, together with NCK, mediates activation of the Arp2/3 complex leading to polymerization of the actin cytoskeleton to form lamellipodia typical of mesenchymal movements as well as tumor metastasis and angiogenesis." (PMID 38033031, 2023). "SF1126 also could suppress integrin-mediated tumor cell migration and block the integrin-induced guanosine diphosphate (GDP)-Rac family small GTPase 1 (Rac1) conversion to its active state." (PMID 37046703, 2023). "Besides, after reconstitution of RAC1 in MG53-overexpressed HCC cells, the anti-tumor effect of MG53 was significantly rescued, which further demonstrated that MG53 exerted its anti-tumor effect by inhibiting RAC1 in HCC cells." (PMID 35858925, 2022). "Of note, in tissue microarray (TMA) samples, 29 of 33 cases demonstrated higher Rac1/Cdc42 activity in the tumor area than the corresponding normal mucosa." (PMID 35110666, 2022). "RAC1 and IQGAP1 were reported to play key roles in regulating tumor cell adhesion." (PMID 35574392, 2022). "Taking the RAC1 story further to support its new role as a downstream regulator of RAB4A in EMT, invasion and sphere formation in in vitro settings, we performed an orthotopic in vivo tumor formation study." (PMID 36307864, 2022). "Rac1 has also been attributed a central role in epithelial to mesenchymal transition (EMT) enhancing the migratory capacity of tumour cells with a negative impact on prognosis." (PMID 36377725, 2022). "We have demonstrated that MG53 induced poly-ubiquitination modification of RAC1 through its RING domain, and we further try to determine whether MG53 exerts the anti-tumor effect by its RING domain." (PMID 35858925, 2022).